RASAL1 (RAS protein activator like 1)
Diseases named in the same sentence as RASAL1 in open-access papers (continued):
Sharing a sentence is not in itself a finding about the gene and the disease.
liver fibrosis (3 papers, 2015 to 2022). "RASAL1-deficient mice showed more CCl4-induced liver fibrosis than did wild-type littermate mice, as indicated by the percentage of fibrotic area according to Masson’s trichrome staining." (PMID 29029395, 2017). "Finally, to determine the biological roles of RASAL1 in liver fibrosis in vivo, we generated RASAL1-deficient mice by targeting the RASAL1 gene." (PMID 29029395, 2017). "We also show that RASAL1-deficient mice are more susceptible to liver fibrosis." (PMID 29029395, 2017). "The Ras GTPase activating protein RASAL1 has been studied in the context of stellate cells and liver fibrosis and has been characterized as an important tumor suppressor by negatively regulating RAS protein signal transduction in HCC." (PMID 35053620, 2022). "In addition, methyl-CpG-binding protein 2, which increases global methylation levels, has been reported to regulate RASAL1 expression in HSCs of liver fibrosis in rats." (PMID 29029395, 2017). "The molecular analyses facilitated identification of the complex regulatory cascades linking the decreased expression of RASAL1 to the fibrotic activation of HSCs, which may contribute to the development of strategies for preventing liver fibrosis." (PMID 29029395, 2017).
lung fibrosis (3 papers, 2021 to 2024). "A recent study showed that lncRNAPCAT29 inhibits pulmonary fibrosis via downregulating RASAL1/ERK1/2 signal pathway, which suppresses the expression levels of MMP2 and MMP9 in alveolar epithelial cells and pulmonary fibroblast cell differentiation." (PMID 33791201, 2021). "In a study by Liu and colleagues in the mice silica‐induced lung fibrosis model, the overexpression of lnc PCAT29 elevated miR‐221 expression, inhibited TGF‐β1 in lung fibroblasts, and slowed the lung fibrosis process through the RASAL1/ERK1/2 signaling pathway." (PMID 38270295, 2024). "RASAL1(RAS protein activator like 1) is a member of the RAS GTPase-activating protein (GAP) family, which participates in cellular proliferation and differentiation and is associated with pulmonary fibrosis, and cancer." (PMID 33791201, 2021).
lymphoma (3 papers, 2019 to 2024). A malignant (clonal) proliferation of B- lymphocytes or T- lymphocytes which involves the lymph nodes, bone marrow and/or extranodal sites. "RASAL1 gene, as a tumour suppressor gene, is normally expressed in many tissues but decreased in breast, liver, lung, oesophageal cancers, lymphoma, nasopharyngeal and oral squamous cell carcinomas." (PMID 36420686, 2022). "Further, the knockdown of Rasal1 in T-cells limits B16 melanoma pulmonary metastasis and the growth of solid EL-4 lymphoma tumors." (PMID 31641113, 2019). "Furthermore, siRNA reduction of Rasal1 expression in T-cells shrinks B16 melanoma and EL-4 lymphoma tumors, concurrent with an increase in CD8 + tumor-infiltrating T-cells expressing granzyme B and interferon γ-1." (PMID 31641113, 2019).
breast carcinoma (2 papers, 2020 to 2024). "We identified germline pathogenic variants in familial breast cancer patients in ROS1 and RASAL1 genes." (PMID 32906649, 2020).
fibrosis (2 papers, 2015 to 2023). the formation of excess fibrous connective tissue in an organ or tissue in a reparative or reactive process. "In the human heart, cardiac fibrosis correlates with aberrant RAS protein activator like 1 (RASAL1) promoter methylation, transcriptional RASAL1 suppression, increased Ras-GTP activity, and increased expression of EndMT markers." (PMID 37893188, 2023).
follicular thyroid cancer (2 papers, 2020 to 2024). "Somatic driver gene point mutations in RASAL1 in follicular thyroid cancer have also been reported." (PMID 32906649, 2020).
hepatocellular carcinoma (2 papers, 2020 to 2024). A malignant tumor that arises from hepatocytes. "Conversely, the long non-coding RNA TUC338, which is highly expressed in hepatocellular carcinoma, downregulates RASAL1 expression through an unclear mechanism, thereby stimulating Ras signaling." (PMID 33096593, 2020). "Inactivation of PITX1 is common in multiple cancers, including prostate, bladder, and hepatocellular carcinoma, correlating with reduced RASAL1 expression and unconstrained Ras activation." (PMID 33096593, 2020).
ossifying fibroma (2 papers, 2017 to 2019). A bone benign neoplasm that is located_in the mouth and results_in an overgrowth of gingival tissue due to irritation or trauma. "Juvenile ossifying fibromas have the potential to evolve into a giant-cell–rich variant of high-grade OS and are shown to be associated with RASAL1 amplification or RASAL1/MDM2 coamplification." (PMID 29244987, 2017).
ovarian adenocarcinoma (2 papers, 2019 to 2022). An adenocarcinoma that arises from the ovary. "Next, we found overexpression of RASAL1 was determined to be largely associated with lower overall survival in ovarian adenocarcinoma samples." (PMID 33817145, 2019). "These conflicting studies have implications in elucidating novel insight as to how RASAL1 affects cancer occurrence and development, including ovarian adenocarcinoma." (PMID 33817145, 2019). "Consistent with previous reports, we also found ovarian adenocarcinoma cell invasion and migration was inhibited accompanied by inhibition of cell proliferation with RASAL1 gene knockdown." (PMID 33817145, 2019). "Experiments showed RASAL1 deletion repressed ovarian adenocarcinoma cell proliferation, migration and invasion." (PMID 33817145, 2019). "RASAL1 expression levels were significantly upregulated in ovarian adenocarcinoma samples (both P < 0.01)." (PMID 33817145, 2019). "In this work, our observations showed that RASAL1 expression is increased in ovarian adenocarcinoma tumor samples compared with normal samples." (PMID 33817145, 2019). "The OS based on the RASAL1 expression level was further analyzed using publicly available data of 377 ovarian adenocarcinoma patients obtained from the TCGA database." (PMID 33817145, 2019). "To investigate the biological functional of RASAL1 in ovarian adenocarcinoma cells, we measured RASAL1 gene expression in ovarian adenocarcinoma cell lines (HEY and A2780) and normal human ovarian adenocarcinoma cells IOSE80 by qRT-PCR." (PMID 33817145, 2019). "We analyzed RASAL1 gene expression in ovarian adenocarcinoma samples and normal samples gained from the GEO and Oncomine databases respectively." (PMID 33817145, 2019). "This study aimed to identify the functional characteristics of RASAL1 in ovarian adenocarcinoma and a potential mechanism of action." (PMID 33817145, 2019). "We first calculated RASAL1 gene expression differences between 12 normal samples and 12 ovarian adenocarcinoma samples obtained from the GEO database." (PMID 33817145, 2019). "Accordingly, deletion of RASAL1 induced a significant reduction of the ERK signaling pathway in the ovarian adenocarcinoma cell line HEY." (PMID 33817145, 2019). "Given that silencing of RASAL1 inhibits the proliferation of ovarian adenocarcinoma cell line HEY, we then investigated cell migration and invasion in HEY transfected with si-RASAL1 using a wound healing assay and a transwell assay." (PMID 33817145, 2019). "RASAL1 expression levels in ovarian adenocarcinoma cell lines (HEY and A2780) were significantly higher (both P < 0.01) compared to the normal cell line, and RASAL1 expression levels in the HEY cell line was much higher than in the A2780 cell line (P < 0.01)." (PMID 33817145, 2019). "Further, knockdown of RASAL1 could significantly impede ovarian adenocarcinoma cell proliferation, invasion, migration, which might work through the MAPK signaling pathway." (PMID 33817145, 2019). "To determine whether RASAL1 manipulates ovarian adenocarcinoma progression, we evaluated the activation of key signaling proteins in the MAPK signaling pathway, including p-ERK and p-MEK." (PMID 33817145, 2019). "The in vitro assays suggested knockdown of RASAL1 could inhibit cell proliferation, cell invasion and migration of ovarian adenocarcinoma." (PMID 33817145, 2019). "Our findings imply that RASAL1 could function as an important factor in promoting oncogenesis for ovarian adenocarcinoma." (PMID 33817145, 2019). "Furthermore, we found that up-regulated RASAL1 expression suggests a worse OS of ovarian adenocarcinoma tumor patients." (PMID 33817145, 2019). "Moreover, the key proteins in the mitogen-activated protein kinase/extracellular signal-regulated kinase (MEK/ERK) signaling pathway were also decreased in ovarian adenocarcinoma cells with RASAL1 silencing." (PMID 33817145, 2019).
ovarian adenocarcinoma (continued). "Furthermore, the biological effect of RASAL1 in ovarian adenocarcinoma cell lines was assessed by Quantitative real time-PCR (qRT-PCR), Cell Counting Kit-8 (CCK-8), western blot, wound healing and transwell assay." (PMID 33817145, 2019). "clarified that RASAL1 was increased in ovarian adenocarcinoma tumorous tissues and HEY cells, which correlated with poor prognosis in ovarian adenocarcinoma patients." (PMID 35498426, 2022). "Collectively, in this study, we clarified that RASAL1 was increased in ovarian adenocarcinoma tumorous tissues and HEY cells, which correlated with poor prognosis in ovarian adenocarcinoma patients." (PMID 33817145, 2019). "Our results indicate that RASAL1 is involved in the regulation of MAPK signaling pathways, probably resulting in inhibition of ovarian adenocarcinoma cell proliferation." (PMID 33817145, 2019).
Alzheimer disease (1 paper, 2024). A progressive, neurodegenerative disease characterized by loss of function and death of nerve cells in several areas of the brain leading to loss of cognitive function such as memory and language. "Rasal1 has been shown as one of the earliest deregulated proteins in hippocampus in Alzheimer’s disease." (PMID 38246997, 2024).
Autoimmunity (1 paper, 2019). The occurrence of an immune reaction against the organism's own cells or tissues. "Rasal1 is a particularly exciting TCR-associated upstream candidate for the anergy induction in transplantation and autoimmunity, given its defined role of the p21ras-ERK pathway in T-cell unresponsiveness." (PMID 31641113, 2019). "Whether the level of Rasal1 inhibition of ZAP-70 is sufficient to elicit effects on thymic differentiation is unclear; however, it may help protect against excess inflammation or autoimmunity and influence T-cell responses to antigens of varying affinities." (PMID 31641113, 2019).
endometrial cancer (1 paper, 2020). Primary or metastatic malignant neoplasm involving the endometrium (mucous membrane that lines the endometrial cavity). "In particular, RASAL1 overexpression resulted significantly correlated with a worse outcome (increased death) in endometrial cancer, whereas NPL overexpression was correlated to a worse outcome in liver and renal cancers." (PMID 32906649, 2020).
glaucoma (1 paper, 2016). Increased pressure in the eyeball due to obstruction of the outflow of aqueous humor. "We suggest that TGFβ1 and RASAL1 have an interacting role in glaucoma, which could perpetuate the associated fibrosis." (PMID 27124111, 2016). "Further, we wished to establish the relationship between TGFβ1, RASAL1 and DNA methylation in TM cells in glaucoma." (PMID 27124111, 2016). "DNA methylation was increased in both glaucoma TM cells, and in normal TM cells subjected to hypoxia, and 5-aza was able to ameliorate the increased TGFβ1 and decreased RASAL1 observed in glaucoma TM cells." (PMID 27124111, 2016). "There was also a significant increase in RASAL1 indicating that decreasing DNMT activity may ameliorate fibrosis in glaucoma, and that this may be through the RASAL1 pathway." (PMID 27124111, 2016). "We hypothesise that the hypoxic environment seen in glaucoma may contribute to the disease fibrosis by changing the global methylation profile of the cells, which subsequently alters the expression of TGFβ1 and RASAL1." (PMID 27124111, 2016).
heart failure (1 paper, 2024). Inability of the heart to pump blood at an adequate rate to meet tissue metabolic requirements. "Studies have demonstrated abnormal methylation induced by TGF-β1 in mouse models of cardiac fibrosis and clinical observations in heart failure patients with reduced Ras protein activator-like 1 (RASAL1) expression, compromising its role in suppressing EndMT." (PMID 38892367, 2024).
lung adenocarcinoma (1 paper, 2024). A carcinoma that arises from the lung and is characterized by the presence of malignant glandular epithelial cells.
lung carcinoma (1 paper, 2021). "The level of CEACAM5 (P < 0.001), CNGB1 (P = 0.001), CSTL1 (P = 0.009), RASAL1 (P < 0.001) expression were higher in lung tissues of patients with lung cancer alone than controls." (PMID 33791201, 2021). "We found the upregulation of RASAL1 expression in patients with lung cancer, and the level of gene expression was further elevated in those coexisting with COPD." (PMID 33791201, 2021). "The level of CEACAM5 (P < 0.001), CNGB1 (P < 0.001), CSTL1 (P < 0.001), RASAL1 (P < 0.001), SLC4A3 (P < 0.001) expression were also increased in lung tissues of patients with lung cancer coexisting COPD compared to controls." (PMID 33791201, 2021). "In addition, the level of CEACAM5 (P = 0.030), CNGB1 (P = 0.042), CSTL1 (P = 0.046), RASAL1 (P = 0.039), SLC4A3 (P = 0.035) expression were higher in patients with lung cancer coexisting COPD than that in patients with lung cancer alone." (PMID 33791201, 2021). "The role of RASAL1 in COPD and lung cancer has not been investigated, which may relate to matrix metalloproteases involving in inflammation and cancer invasion and metastasis CNGB1 (cyclic nucleotide gated channel subunit beta 1) encodes a cyclic nucleotide gated channel." (PMID 33791201, 2021).
ovarian carcinoma (1 paper, 2019). A malignant neoplasm originating from the surface ovarian epithelium. "To gain insight into the effect of RASAL1 inhibition on ovarian cancer progression, we evaluated the effect of RASAL1 on tumor growth using bioinformatics analysis and in vitro experiments respectively." (PMID 33817145, 2019). "In vitro knockdown of RASAL1 demonstrated the oncogenic role of RASAL1 in ovarian cancer invasion and metastasis." (PMID 33817145, 2019). "We further assessed the biological effect and mechanism of action of RASAL1 on human ovarian cancer cell lines." (PMID 33817145, 2019). "The contradictory roles of RASAL1 in ovarian cancer underscore an important contextual dependency of RASAL1 function in human cancers." (PMID 33817145, 2019). "In the bioinformatics analysis, we determined the clinical implications between RASAL1 expression and prognosis of ovarian cancer." (PMID 33817145, 2019). "In terms of mechanism, we showed that the oncogenic function of RASAL1 in ovarian cancer also influenced MAPK signaling as RASAL1 depletion attenuates the activity of key proteins p-ERK and p-MEK in ovarian cancer cells HEY." (PMID 33817145, 2019). "As of yet, the relationship between RASAL1 and ovarian cancer has not been unambiguously determined." (PMID 33817145, 2019).
ovarian serous adenocarcinoma (1 paper, 2019). An adenocarcinoma that arises from the ovary and is characterized by the presence of malignant epithelial cells that, in well differentiated tumors, resemble the epithelium of the fallopian tube or, in poorly differentiated tumors, show anaplastic features and marked nuclear atypia. "Then we analyzed RASAL1 gene expression differences between 10 peritoneum samples and 43 ovarian serous adenocarcinoma samples obtained from the oncomine database." (PMID 33817145, 2019). "Similarly, RASAL2 is functionally equivalent with RASAL1 upregulation and gene copy number gain which is also found in high-grade serous ovarian cancer, and has recently been found to share a similar molecular portrait to TNBC through large-scale genomic analyses." (PMID 33817145, 2019).
papillary thyroid cancer (1 paper, 2024). "Consistent with the present study, we previously found hardly mutations in RASAL1 in papillary thyroid cancer (PTC), but found inactivating RASAL1 mutations in FTC and ATC although RASAL1 hypermethylation was common in PTC." (PMID 39032134, 2024).
sarcoidosis (1 paper, 2025). Sarcoidosis is a multisystemic disorder of unknown cause characterized by the formation of immune granulomas in involved organs. "Among the twelve common DEGs, SALL4, WNT10A, RASAL1, CAMK2B were significantly upregulated while GADD45B, KLF4, OLR1, CSF3, WIF1, RAMP3 and AGER downregulated in both sarcoidosis and LC as compared to the controls." (PMID 40797277, 2025).